S1PR1 (sphingosine-1-phosphate receptor 1)
Diseases named in the same sentence as S1PR1 in open-access papers (continued):
Sharing a sentence is not in itself a finding about the gene and the disease.
hepatocellular carcinoma (18 papers, 2014 to 2025). A malignant tumor that arises from hepatocytes. "We observed that the expression of S1PR1 in hepatoma cells was lower than that in paratumor liver cells, which was different from the results in another report." (PMID 36068200, 2022). "Conditioned HUVEC medium consequently provided a four-fold enhanced calcium signal in S1PR1, overexpressing rat hepatoma HTC4 cells compared to EA.hy926 conditioned medium." (PMID 32290092, 2020). "Conditioned HUVEC medium consequently reduced the calcium signal by 60% in S1PR1 overexpressing rat hepatoma HTC4 cells after treatment with cytokines and LPS compared to non-treated HUVEC medium." (PMID 32290092, 2020). "Mechanistically, we showed that ERO1α prompted angiogenesis, migration, and invasion of hepatoma cells via the S1PR1/STAT3/VEGF-A signaling pathway both in vitro and in vivo." (PMID 30377291, 2018). "In the present study, the expression level of miR-148a was shown to be notably reduced in hepatocellular carcinoma tissues and cells compared with that in normal tissues; however, the protein expression of S1PR1 was markedly upregulated." (PMID 25574238, 2015). "Accordingly, the present data suggest that miR-148a is downregulated whereas S1PR1 is upregulated in hepatocellular carcinoma." (PMID 25574238, 2015). "In the present study, it was shown that S1PR1 was significantly upregulated in hepatocellular carcinoma tissues, consistent with a previous study." (PMID 25574238, 2015). "In the present study, S1PR1 was found to be involved in the miR-148a-mediated inhibition of hepatocellular carcinoma invasion." (PMID 25574238, 2015). "Based on these findings we suggest that S1PR1 acts as a downstream effector in the miR-148a-induced inhibition of hepatocellular carcinoma cell invasion." (PMID 25574238, 2015). "The protein expression of S1PR1 was determined by performing western blotting, which showed that the protein level of S1PR1 was upregulated in the hepatocellular carcinoma tissues compared with that in their matched normal adjacent tissues." (PMID 25574238, 2015). "Further investigation identified S1PR1 as a direct target of miR-148a, and the protein expression of S1PR1 was negatively regulated by miR-148a in hepatocellular carcinoma cells." (PMID 25574238, 2015). "Accordingly, the current study suggests that miR-148a plays an inhibitory role in the regulation of hepatocellular carcinoma cell invasion by directly targeting S1PR1." (PMID 25574238, 2015). "Furthermore, miR-363-3p suppresses the proliferation of human hepatocellular carcinoma cells by targeting S1PR1 or USP28." (PMID 33744854, 2021). "Based on previous and the current findings, we suggest that S1PR1 could become an effective target for the prevention of hepatocellular carcinoma metastasis." (PMID 25574238, 2015). "In addition, miR-363 is known to target many genes in addition to GATA6, including S1PR1, which is crucial for the growth of hepatocellular carcinoma cells." (PMID 26387746, 2015). "The inhibition of S1PR1 expression in HepG2 cells was used to determine whether miR-148a played a suppressive role in hepatocellular carcinoma cell invasion." (PMID 25574238, 2015). "In addition, the current study suggested that the suppressive effect of miR-148a on hepatocellular carcinoma cell invasion is, at least partly, via the inhibition of S1PR1." (PMID 25574238, 2015). "Furthermore, it was shown that S1PR1 was an important downstream effector of the miR-148a-induced inhibition of cell invasion in hepatocellular carcinoma HepG2 cells." (PMID 25574238, 2015). "At present, FTY720 is regarded as a novel immunosuppressant with potent anticancer properties In the MCA-RH7777 hepatocellular carcinoma cell line model, FTY720 reduced intrahepatic and pulmonary metastases as well as tumorigenesis, possibly through its function as an S1PR1 modulator." (PMID 39935473, 2025).
ovarian carcinoma (17 papers, 2011 to 2023). A malignant neoplasm originating from the surface ovarian epithelium. "We also found that PDK1 expression decreased significantly, and cell senescence increased in S1PR1-deficient ovarian cancer cells." (PMID 37828220, 2023). "The high expression of S1PR1 in ovarian cancer tissues and cells was further linked to chemotherapy resistance." (PMID 37828220, 2023). "After silencing LATS1/2 in S1PR1-deficient ovarian cancer cells, senescence was suppressed and S1PR1 expression was increased concomitantly with YAP expression." (PMID 37828220, 2023). "Moreover, S1PR1 expression is more significant in stages III-IV, high-grade lymph node metastases, and distant metastases of ovarian cancer, and S1PR1/3 is strongly associated with angiogenesis in ovarian cancer." (PMID 37828220, 2023). "We found that S1PR1 deletion resulted in decreased proliferation and migration of ovarian cancer cells and cell cycle arrest in the G1 phase." (PMID 37828220, 2023). "Our results showed that, after S1PR1 knockdown in ovarian cancer cells, the expression of LATS1/2 was significantly increased, the level of phosphorylated YAP was increased, and the expression of PDK1 was significantly decreased." (PMID 37828220, 2023). "Sphingolipids are multifaceted mediators in ovarian cancer, and the sphingosine kinase 1-sphingosine 1-phosphate receptor 1 axis is altered in ovarian cancer in multiple ways and therefore represents an attractive therapeutic target." (PMID 37684587, 2023). "To further verify the role of LATS1/2 in ovarian cancer cell senescence, we silenced LATS1 and LATS2 in S1PR1 knockout ovarian cancer cells." (PMID 37828220, 2023). "In this study, we demonstrate that S1PR1 was highly expressed in human ovarian cancer tissues and cell lines." (PMID 37828220, 2023). "S1PR1 deletion promoted ovarian cancer cell senescence and sensitized ovarian cancer cells to cisplatin chemotherapy." (PMID 37828220, 2023). "Collectively, our results suggest that the Hippo pathway is regulated by S1PR1 and contributes to ovarian cancer cell senescence." (PMID 37828220, 2023). "We therefore investigated S1PR1 expression patterns in human ovarian cancer and the role of S1PR1 in cell cycle regulation, proliferation, and senescence in cultured cells and a xenograft mouse model." (PMID 37828220, 2023). "S1P treatment or S1PR1 deletion showed that the PDK1-LATS1/2-YAP pathway was involved in ovarian cancer cell senescence, consistent with the in vivo results." (PMID 37828220, 2023). "Western blotting showed that S1PR1 was highly expressed in ovarian cancer tissues (n = 4), but mildly expressed in paracancerous tissues (n = 2)." (PMID 37828220, 2023). "YAP bound to the S1PR1 gene in ovarian cancer cells, while S1PR1 deletion resulted in a significant decrease in YAP binding to the S1PR1 promoter." (PMID 37828220, 2023). "Immunohistochemical analysis evinced that S1PR1 expression was higher in chemoresistant ovarian cancer tissues than in chemosensitive ovarian cancer tissues." (PMID 37828220, 2023). "The decrease in S1PR1 expression in ovarian cancer cells promoted senescence and enhanced chemotherapeutic efficacy of cisplatin." (PMID 37828220, 2023). "S1PR1 is expected to be a druggable target that can improve ovarian cancer chemotherapy by promoting ovarian cancer cell senescence." (PMID 37828220, 2023). "We observed that S1PR1 was highly expressed in human ovarian cancer tissues (n = 6), but relatively low in normal ovarian tissues (n = 2)." (PMID 37828220, 2023).
ovarian carcinoma (continued). "S1PR1 is upregulated in ovarian cancer tissues and cell lines, which is negatively regulated by miR-148a in EOC cells." (PMID 29987226, 2018). "Collectively, our findings presented evidence that the SphK1/S1P/S1PR1/3 axis played a critical role in regulating ovarian cancer angiogenesis." (PMID 29088837, 2017). "For example, activated S1PR1 leads to the migration of ovarian cancer cells via PKC and RhoA signaling." (PMID 28831167, 2017). "Collectively, the current study showed a novel role of SphK1/S1P/S1PR1/3 axis within the ovarian cancer, suggesting a new target to block ovarian cancer angiogenesis." (PMID 29088837, 2017). "In view of the function of S1PR1/3 in S1P-induced angiogenic factor secretion, we further determined its roles in the angiogenic potential of ovarian cancer." (PMID 29088837, 2017). "Together, these results provided evidence that both S1P and S1PR1/3 are responsible for the angiogenic factor secretion and the angiogenic potential of ovarian cancer." (PMID 29088837, 2017). "Here we provided the first evidence that SphK1/S1P/S1PR1/3 pathway played key roles in ovarian cancer angiogenesis." (PMID 29088837, 2017). "Several studies have demonstrated that SP1/S1PR1 modulated cell growth, adhesion, migration, and invasion in ovarian cancer cells." (PMID 28831167, 2017). "In ovarian cancer, we observed that 55% (11/20) samples displayed high S1PR1 level, 80% (16/20) samples showed high S1PR2 level and 75% (15/20) samples showed high S1PR3 level." (PMID 29088837, 2017). "This supports previous observations and suggests that S1PR1-induced expression of STAT3 is part of a positive feedback loop resulting in persistent STAT3 activation in ovarian cancer." (PMID 25594014, 2014). "When investigating whether S1PR1 and CDDP resistance are related to senescence regulation in ovarian cancer, we found that S1PR1 expression was enhanced in both cisplatin-resistant ovarian cancer tissues and cisplatin-resistant ovarian cancer cells." (PMID 37828220, 2023). "The mechanism by which S1PR1 regulates ovarian cancer cell senescence is currently elusive." (PMID 37828220, 2023). "To investigate whether S1PR1 can affect ovarian cancer chemotherapy resistance through senescence, we first detected its expression in tissues from chemoresistant patients (CDDP-resistant) and chemosensitive patients (CDDP-sensitive)." (PMID 37828220, 2023). "The expression of LATS1/2 was significantly increased in S1PR1-deleted ovarian cancer cells." (PMID 37828220, 2023). "LATS1/2 silencing in S1PR1 knockout cells significantly promoted ovarian cancer cell proliferation." (PMID 37828220, 2023). "S1PR1 constitutes a druggable target for the induction of senescence in ovarian cancer cells." (PMID 37828220, 2023). "S1PR1 expression was partially reduced in ovarian cancer cells." (PMID 37828220, 2023). "Our study demonstrated that S1PR1 inhibits ovarian cancer cell senescence." (PMID 37828220, 2023). "Corroboratively, silencing P21 also decreased senescence in S1PR1-deleted ovarian cancer cells." (PMID 37828220, 2023). "S1PR1 knockdown promoted cisplatin-induced apoptosis of ovarian cancer cells." (PMID 37828220, 2023). "S1PR1 deletion promoted senescence in ovarian cancer cells treated with cisplatin." (PMID 37828220, 2023). "Moreover, silencing LATS1/2 in S1PR1 knockout cells significantly decreased ovarian cancer cell senescence as per β-galactosidase staining." (PMID 37828220, 2023).
ovarian carcinoma (continued). "S1PR1 inhibition increases the sensitivity of ovarian cancer cells to CDDP by inducing senescence and may also provide a novel strategy to treat chemotherapy-resistant ovarian cancer." (PMID 37828220, 2023). "In ovarian cancer, the S1P/S1PR1/3 pathway is involved in regulating angiogenesis." (PMID 37828220, 2023). "S1PR1 deletion inhibited the proliferation and migration of ovarian cancer cells." (PMID 37828220, 2023). "This study revealed that S1PR1 is highly expressed in ovarian cancer tissues and cell lines." (PMID 37828220, 2023). "An altered SphK1/S1P/S1PR1/3 signaling axis could play a crucial role in ovarian cancer angiogenesis, although further explorations on intracellular S1P functions should be conducted, keeping in mind its biological action exerted due to S1PR binding." (PMID 36362323, 2022). "S1PR1 expression was lower in most tumor tissues, including sarcoma, bladder, brain, central nervous system, breast, colorectal, leukemia, lung, myeloma, and ovarian cancer tissues, than in normal tissues." (PMID 32799825, 2020). "in vivo, blockage of SphK or S1PR1/3 could attenuate ovarian cancer angiogenesis and inhibit angiogenic factor expression in mouse models." (PMID 29088837, 2017). "The results showed a novel role of SphK1/S1P/S1PR1/3 axis within the ovarian cancer." (PMID 29088837, 2017). "In the current study, we provided evidence that SphK1/S1P/S1PR1/3 signaling played an important role in ovarian cancer angiogenesis and blockage of this pathway could significantly inhibit the angiogenic process of the cancer." (PMID 29088837, 2017). "SphK1 could control the release of S1P, which was able to promote the secretion of some proangiogenic cytokines in ovarian cancer cells via S1PR1 and S1PR3." (PMID 29088837, 2017). "We found S1PR1-3 were overexpressed in ovarian cancer tissues." (PMID 29088837, 2017). "S1PR1/3 blockage suppressed the angiogenic factor secretion of ovarian cancer cells." (PMID 29088837, 2017). "Thus, we sought to examine the expression of S1PR1 in human ovarian cancer, and found that S1PR1 is consistently expressed in human ovarian cancer samples." (PMID 25594014, 2014). "Whether S1PR1 regulates senescence in ovarian cancer cells is presently unknown." (PMID 37828220, 2023). "This suggests that S1PR1 may play a role in resistance of ovarian cancer cells to chemotherapy." (PMID 37828220, 2023). "In addition, levels of IGFBP7, PAI-1, lamin B1, P21, P27, P62, p-H2AX, and other factors related to cell senescence were significantly elevated, indicating that S1PR1 may be involved in regulating ovarian cancer senescence." (PMID 37828220, 2023). "In addition, S1PR1 knockdown promoted cisplatin-induced apoptosis of ovarian cancer cells." (PMID 37828220, 2023). "However, whether S1PR1 can regulate aging through PDK1 in ovarian cancer cells and whether LATS1/2 and YAP are involved in this regulation has not been reported." (PMID 37828220, 2023). "Immunofluorescence staining showed that S1PR1 protein was localized on the cell membrane of SKOV3, OVCAR-3, HO8910, ES-2, A2780, and C13 ovarian cancer cells." (PMID 37828220, 2023). "In a complementary approach, we used siRNAs specific to SPHK1, S1PR1, and S1PR2 to knock down those proteins’ expression in ovarian cancer cells." (PMID 35289120, 2022). "Further the expression of SPHK1 and S1PR1/3 was correlated with microvascular density of ovarian cancer tissue, and inhibition of SPHK1 or S1PR1/3 attenuated angiogenic potential and angiogenic factor secretion of ovarian cancer cells in vitro and in vivo." (PMID 31891125, 2018).
ovarian carcinoma (continued). "The culture medium prepared from S1PR1/3 antagonist, VPC23019, pretreated ovarian cancer cells significantly inhibited endothelial cell migration, invasion and tube formation." (PMID 29088837, 2017). "Specifically, we demonstrate that increasing S1PR1 expression in HOCCs initiates STAT3 activation, resulting in enhanced ovarian cancer cell survival and proliferation under hypoxic conditions both in vitro and in vivo." (PMID 25594014, 2014). "While the expression of NOG, S1PR1, BTG4, and CREB5 genes was significantly increased, that of RASSF9, DNMT1, BST2, and SETD1A genes was significantly decreased in CFP1-deleted A2780 and ES-2 ovarian cancer cells, based on qRT-PCR results." (PMID 35864225, 2022). "To verify whether CFP1 protein affects ovarian cancer cell proliferation through NOG and S1PR1 genes, we silenced both genes in CFP1-deleted cells by siRNA, and the expression of NOG and S1PR1 genes was significantly decreased as revealed by qRT-PCR." (PMID 35864225, 2022). "We previously found that S1PR1, S1PR2 and S1PR3 were overexpressed in ovarian cancer tissue." (PMID 33931106, 2021). "Because S1PR1 and S1PR3 mediated S1P-induced angiogenic factor secretion in ovarian cancer cells, we wanted to determine whether they are responsible for the angiogenic potential of the cells." (PMID 29088837, 2017). "In addition, we show that S1PR1, a regulator of STAT3 transcription via the JAK/STAT pathway, is highly expressed in hypoxic ovarian cancer cells (HOCCs)." (PMID 25594014, 2014). "The schematic diagram of the molecular mechanism shows that, when S1PR1 is activated by S1P or a related agonist in ovarian cancer cells, PDK1 expression is increased, LATS1/2 expression is inhibited, and YAP expression is increased, thereby inhibiting ovarian cancer cell senescence." (PMID 37828220, 2023). "Collectively, S1PR1 is overexpressed in ovarian cancer tissues and cells compared to non-cancerous controls and may therefore play a role in ovarian cancer biology." (PMID 37828220, 2023). "Indeed, S1P induced the angiogenic factor expression via S1PR1 and S1PR3 in ovarian cancer cells; in fact, blocking SphK or S1PR1/3 might functionally inhibit ovarian cancer angiogenesis." (PMID 36362323, 2022). "Blockage of SphK1, but not SphK2, or S1PR1/3 could attenuate ovarian cancer angiogenesis and inhibit angiogenic factor expression in a mouse model." (PMID 29987226, 2018). "Our results showed that down-regulation of S1PR1 or S1PR3, but not S1PR2, effectively inhibited S1P-induced VEGF, IL-8 and IL-6 secretion in ovarian cancer cells." (PMID 29088837, 2017). "We found that S1PR1 and S1PR3, but not S1PR2, were responsible for the angiogenic potential and angiogenic factor secretion of ovarian cancer cells in vitro." (PMID 29088837, 2017).